GDF3 (growth differentiation factor 3)
Description:
Growth factor involved in early embryonic development and adipose-tissue homeostasis. During embryogenesis controls formation of anterior visceral endoderm and mesoderm and the establishment of anterior-posterior identity through a receptor complex comprising the receptor ACVR1B and the coreceptor CRIPTO (By similarity). Regulates adipose-tissue homeostasis and energy balance under nutrient overload in part by signaling through the receptor complex based on ACVR1C and CRIPTO/Cripto.
Synonyms: KFS3; MCOP7; MCOPCB6
Tractability: Antibody: UniProt places it where antibodies can reach, with high confidence; UniProt predicts a signal peptide or a membrane-spanning region; its Gene Ontology location is reachable by antibodies, with medium confidence.
Gene: Protein-coding gene on chromosome 12 (7,689,784 to 7,695,775, reverse strand). Ensembl gene ENSG00000184344.
Subcellular location: Secreted; Cytoplasm
Gene Ontology:
Molecular function: protein kinase binding; cytokine activity; growth factor activity
Biological process: eye development; negative regulation of BMP signaling pathway; negative regulation of epidermal cell differentiation; regulation of cell fate commitment; skeletal system development; BMP signaling pathway; positive regulation of fat cell differentiation; animal organ development; regulation of transmembrane receptor protein serine/threonine kinase signaling pathway
Cellular component: cytoplasm; extracellular region
Genetic constraint (gnomAD): Loss-of-function variants: 9 observed, 10.29 expected, observed/expected ratio (o/e) 0.87, 90% interval 0.53 to 1.51. The upper end of that interval is the gene's LOEUF score, 1.51, which puts it in group 6 of 6, group 1 being the genes least tolerant of losing a copy. Missense variants: 440 observed, 449.89 expected, observed/expected ratio (o/e) 0.98, 90% interval 0.9 to 1.06. Synonymous variants: 163 observed, 184.55 expected, observed/expected ratio (o/e) 0.88, 90% interval 0.78 to 1.01.
Homologues: Orthologues: chimpanzee GDF3 (99% identical), macaque GDF3 (96% identical), pig GDF3 (81% identical), dog GDF3 (80% identical), rabbit GDF3 (78% identical), mouse Gdf3 (70% identical), rat Gdf3 (68% identical). Paralogues in human: GDF1 (35% identical), BMP2 (27% identical), GDF5 (27% identical), BMP4 (26% identical), BMP6 (24% identical), GDF6 (24% identical), BMP8A (24% identical), BMP8B (24% identical), BMP7 (23% identical), BMP5 (22% identical), GDF2 (22% identical), BMP10 (21% identical), and 19 more.
Diseases named in the same sentence as GDF3 in open-access papers:
GDF3 is named in the same sentence as 44 diseases in open-access papers, as found by Europe PMC text mining. Sharing a sentence is not in itself a finding about the gene and the disease. The quoted sentences say what the papers report.
Obesity (16 papers, 2009 to 2025). Accumulation of substantial excess body fat. "This study aims to investigate the impact of GDF3 and associated metabolic effects on diet-induced obesity in mice." (PMID 40360531, 2025). "In conclusion, our study shows that deletion of the obesity associated gene Gdf3, leads to reduced lipolysis and improved metabolic health in obese mice, with no change in body weight." (PMID 40360531, 2025). "We conducted the study using inducible Gdf3 knockout mice to examine the effects of GDF3 loss of function after the onset of diet-induced obesity." (PMID 40360531, 2025). "Apart from the key characterization of GDF3 as a stem cell marker, it is currently introduced as an adipogenic cytokine that is associated with the obesity process." (PMID 37205315, 2023). "The increased expression of GDF3 observed in obesity may contribute to pathologies linked to “BMP resistance”—where despite increasing circulating levels of ligands, BMP signaling is diminished." (PMID 40360531, 2025). "GDF3 was recently reported to be associated with obesity and systemic insulin resistance." (PMID 39872077, 2022). "In adult humans and mice, Gdf3 mRNA levels significantly increase in obesity, aging, inflammation, and following an ischemic event." (PMID 40360531, 2025). "Growth differentiation factor 3 (Gdf3) is a protein in the TGFβ superfamily and found in increased levels in obesity, aging and inflammation." (PMID 40751023, 2025). "This study, using the first conditional deletion of GDF3, provides new insights to understand the role of GDF3 in the pathogenesis of obesity and metabolic dysregulation." (PMID 40360531, 2025). "Studies have shown that GDF3 regulates adipose tissue accumulation and high-fat-diet-induced obesity through ALK7-signaling pathways." (PMID 39936965, 2025). "This approach allowed us to conditionally delete Gdf3 with tamoxifen-induced Cre recombinase after the development of obesity." (PMID 40360531, 2025). "The study had shown that Brd4 binds to the promoter and enhancer of GdF3 to promote PPARγ-dependent expression of GdF3 in macrophages and modulated lipid metabolism and diet-induced obesity." (PMID 36741233, 2023). "Specifically, Brd4 cooperates with PPARγ in ATMs to regulate the expression of Gdf3, which acts on the adipocytes to suppress the expression of lipases and lipolysis, resulting in fat accumulation and the development of obesity." (PMID 33830083, 2021). "This study further suggests that decoy ACVR2A/2B receptor drugs being considered for anti-obesity co-therapies with GLP1-agonist drugs might additionally involve the suppression of GDF3 signaling and warrant further exploration." (PMID 40360531, 2025). "GDF3 levels are low in lean healthy adult mice but rapidly increase with obesity or ischemia." (PMID 40360531, 2025). "Gdf-3 has been identified as an important pathway for promoting insulin sensitivity in the S273A knockin lineage developed by homologous recombination in mESCs, which indicates a promising target for diabetes and obesity modulation." (PMID 37189379, 2023). "Overweight individuals (BMI ≥ 25) have higher Brd4 expression in blood samples than individuals with normal weight, and the expression levels of Brd4 positively correlate with the expression of Gdf3 in obese individuals, highlighting the importance of Brd4-Gdf3 regulatory pathway in obesity." (PMID 33830083, 2021). "Controlling the expression of Gdf3 in ATMs could be one of the mechanisms by which Brd4 modulates lipid metabolism and diet-induced obesity." (PMID 33830083, 2021). "Another inflammatory candidate that might affect BAT biology and thermogenesis is the macrophage secreted factor GDF3 (growth differentiation factor-3) which increases in obesity." (PMID 32265845, 2020). "Finally, we evaluated the relevance of Brd4 and Gdf3 to obesity in human patients." (PMID 33830083, 2021).
Obesity (continued). "Gdf3 knockout mice displayed less accumulated adipose tissue than WT mice and showed partial resistance to HFD-induced obesity." (PMID 33830083, 2021). "Similar to Gdf3 knockout mice, Brd4-CKO mice had similar reduced fat accumulation and were resistance to HFD-induced obesity." (PMID 33830083, 2021). "GDF3, ALK7 and co-receptor Cripto are all expressed in adipose tissues, and Gdf3(-/-) null mice and ALK7(-/-) null mice showed reduced fat accumulation and resistance to diet-induced obesity." (PMID 19538713, 2009).
breast carcinoma (12 papers, 2006 to 2025). "It has been shown that the GDF3 knockdown in human breast cancer cells can cause the propagation of colony formation and tumor progression, while its overexpression can promote apoptosis." (PMID 37205315, 2023). "GDF3 is expressed in several malignancies such as melanoma, teratocarcinoma, testicular germ cell tumors (TGCTs), seminoma, and breast carcinoma." (PMID 37205315, 2023). "GDF3 is widely accepted as a pluripotency marker and expressed in several cancer types such as breast carcinoma melanoma." (PMID 35361267, 2022). "GDF3 was upregulated in 4/24 breast cancers compared to paired normal, and downregulated in 12/24, but no information on ER status of the studied patients was available." (PMID 25004928, 2014). "It was demonstrated, that GDF3 inhibits the proliferation of breast carcinoma cell line MCF7, but augments proliferation of B16 myeloma and can promote neuronal differentiation of PC12 cells." (PMID 23950971, 2013). "Along with other embryonic stem cell markers, GDF3 was shown to be expressed in several cancer types such as breast carcinoma, melanoma, seminoma and testicular germ cell tumors." (PMID 23950971, 2013). "GDF3 has been already reported to be expressed in breast cancer, although the expression level seem to be reduced in comparison to the surrounding, healthy tissue." (PMID 23950971, 2013). "Human GDF3 is primarily expressed in embryonal carcinomas, testicular germ cell tumors, seminomas, and breast carcinomas." (PMID 20950440, 2010). "GDF3 expression was observed in embryonal carcinomas, primary testicular germ cell tumors, seminomas and breast carcinomas." (PMID 20950440, 2010). "GDF3 expression is also found in primary testicular germ cell tumors, seminomas, and breast carcinomas." (PMID 20950440, 2010). "Moreover, GDF3 played a paradoxical role in cancer that it inhibited the growth of breast cancer cells and promotes paclitaxel-induced apoptosis; on the other hand, it promoted the progression of melanoma." (PMID 36172369, 2022). "Interestingly, another putative stem cell gene, GDF-3, has been found to be expressed in both seminomas and breast carcinomas." (PMID 31565104, 2019). "It would be interesting to investigate, whether the restoration of GDF3 level in breast cancer would increase HOXA9 expression and thereby reduce malignancy of disease and improve the clinical outcome for the patient." (PMID 23950971, 2013). "It has been indicated that GDF3 augments the progression of B16 melanoma and can enhance neuronal differentiation of PC12 cells, but inhibits the proliferation of breast carcinoma cell line MCF7." (PMID 37205315, 2023). "Several research groups have already tried to decipher the role of GDF3 in ESC biology, breast carcinoma and myeloma, and have yielded contradictory results." (PMID 23950971, 2013). "Human embryonic stem cell genes NANOG, GDF3 and STELLA, which are downregulated when cells commit differentiation, are expressed in TGCT and in breast cancers." (PMID 17040570, 2006). "Two embryonic stem cell genes, GDF3 and NANOG, were shown to be expressed in breast cancer." (PMID 25004928, 2014).
seminoma (7 papers, 2010 to 2023). A radiosensitive malignant germ cell tumor found in the testis (especially undescended), and extragonadal sites (anterior mediastinum and pineal gland). "It has been determined that in primary TGCTs GDF3 expression is low in seminomas, while its expression in non-seminomas is easily acquirable and appeared to be correlated with the embryonal carcinoma and yolk sac components in the tumors." (PMID 37205315, 2023). "Among them, GDF3, NODAL, LEFTY1 /2, GAL, DPPA3, SOX2, DNMT3B /L, DPPA5, BCAT1, FGF2, PRDM14, ZIC3 and FZD7, while seminoma markers SOX17, cKIT and PRAME were downregulated." (PMID 26226633, 2015). "Expression of typical seminoma markers (PRDM1/BLIMP1, SOX17, PRAME, TFAP2C) was also detectable in TCam-2-ΔSOX2/FOXA2 tumor tissues, in contrast to EC reprogramming factors (GDF3, DPPA3, DNMT3B, GAL), which could only be detected in 2102EP in vivo or reprogrammed TCam-2 cells." (PMID 31130628, 2019). "GDF3 hypermethylation is restricted to parental TCam-2, but not seen in seminomas or EC cells." (PMID 26226633, 2015). "Furthermore, seminomas have elevated levels of GDF3 expression compared to the normal testis, as well as other stem cell markers such as Nanog homeobox (NANOG) and octamer-binding transcription factor 4 (OCT4), and in particular DAZL (a germ cell-specific marker)." (PMID 37205315, 2023).
embryonal carcinoma (6 papers, 2010 to 2023). A non-seminomatous malignant germ cell tumor characterized by the presence of large germ cells with abundant cytoplasm resembling epithelial cells, geographic necrosis, high mitotic activity, and pseudoglandular and pseudopapillary structures formation. "GDF3 has been identified in Activin-treated embryonic carcinoma cells, and it contributes to the maintenance of hESCs." (PMID 23383118, 2013). "To establish the embryonal carcinoma cell line NCCIT as a suitable CSC model to study the role of GDF3, we evaluated the expression of important components of GDF3 signaling pathway by RT-PCR." (PMID 23950971, 2013). "Additionally, GDF3 is a direct transcriptional target of NANOG in embryonic carcinoma cells." (PMID 37205315, 2023). "We confirmed that GDF3 and its receptors are expressed not only in NCCIT cells, but also in another, well-characterized embryonal carcinoma cell line NTERA2." (PMID 23950971, 2013).
Insulin resistance (6 papers, 2021 to 2025). Increased resistance towards insulin, that is, diminished effectiveness of insulin in reducing blood glucose levels. "In each instance, high GDF3 levels positively correlate with insulin resistance, while low GDF3 levels are associated with insulin sensitivity." (PMID 40360531, 2025). "Nonetheless, the underlying mechanisms of the relationship between insulin resistance and S273 phosphorylation are still largely unknown, except for the involvement of growth differentiation factor (GDF3) regulation in the process." (PMID 37189379, 2023). "Phosphorylation of PPARγ at S273 induces insulin resistance by upregulating Gdf3 expression and inhibiting BMP signaling pathway." (PMID 37143582, 2023). "These authors proposed that, as a result of increased expression of miRNA-483-3p, GDF3 is downregulated which in turn affects the ability of adipose cells to store lipids and ultimately leads to insulin resistance." (PMID 35271586, 2022). "Loss of GDF3 as an ALK7 receptor agonist should produce lower fat mass and insulin resistance." (PMID 40360531, 2025). "Conversely, GDF3 gain of function increases rates of lipolysis and insulin resistance." (PMID 40360531, 2025). "Because eWAT and prWAT are linked to insulin resistance and type 2 diabetes, the reduced size of WAT from increased lipolysis triggered by Gdf3 reduction might account for the improved insulin sensitivity in Brd4-CKO mice." (PMID 33830083, 2021). "Brd4 occupied the promoter and enhancers of Gdf3 to facilitate PPARγ-dependent expression of Gdf3, which in turn suppressed ATGL expression and lipolysis in adipocytes, resulting in the increased fat accumulation and insulin resistance." (PMID 33830083, 2021). "However, acute GDF3 gain-of-function in lean mice led to mild glucose intolerance and insulin resistance with no change in body weight." (PMID 40360531, 2025).
melanoma (5 papers, 2010 to 2023). A malignant, usually aggressive tumor composed of atypical, neoplastic melanocytes. "We have shown that GDF3 mRNA increased during tumorigenesis in mouse melanoma B16-F1 and B16-F10 cells." (PMID 20950440, 2010). "We examined the expression of CD133, CD44, CD24, and ABCB5 during tumorigenesis of B16 melanoma cells transfected with empty or GDF3-expressing vectors." (PMID 20950440, 2010). "The expression profiles of CD24 in B16 melanoma sublines were parallel to those of GDF3, but hepatoma lines G1 and G5 had impaired the ability to induce GDF3-mediated CD24 expression." (PMID 20950440, 2010). "Unlike B16 melanoma cells, forced expression of GDF3 did not result in acceleration of tumor growth in G1 or G5 cells, indicating that the ability of GDF3 to promote tumorigenesis is specific to B16 melanoma that expresses GDF3 during s.c. progression." (PMID 20950440, 2010). "Using mouse melanoma B16-F1 and B16-F10 cell lines as a model system, we found that GDF3 expression is different in these B16 sublines during tumor progression." (PMID 20950440, 2010). "Our present finding furthers this notion and suggests that constitutive or forced expression of GDF3 in melanoma cells links the high CD24 expression accelerating tumor growth." (PMID 20950440, 2010). "Overexpression of GDF3 promoted growth of implanted melanoma B16 F1 and F10 in syngenic mice." (PMID 20950440, 2010). "Finally, our results support the view that GDF3 has the ability to induce progression of CD24-inducible melanoma in mice." (PMID 20950440, 2010). "Besides SOX2, GDF3 has been shown to stimulate CD24 expression in melanoma cells." (PMID 34293822, 2022). "As the signal axis of this GDF3-derived CD24-inducing pathway is undetermined, it remains unsettled as to what is the molecular discrepancy between B16 F1/F10 melanoma cells and G-1/G5 hepatoma cells." (PMID 20950440, 2010). "Interestingly, B16-F1 and B16-F10 cells induced expression of CD133, ABCB5, CD44 and CD24, which are expressed in mouse melanoma CSC-like cells during tumorigenesis, and ectopic generation of GDF3 increased the CD24 expression." (PMID 20950440, 2010). "We found that GDF3 overexpression promotes tumorigenesis of mouse melanoma by B16-F1 and B16-F-10 cells but not hepatoma by G1 or G5 cells." (PMID 20950440, 2010). "To examine whether GDF3 promotes tumorigenesis of not only GDF3-expressing B16 melanomas but also tumors with no expression of GDF3, we transfected the mouse hepatoma G1 or G5 cell lines with empty or GDF3-expressing vectors, and injected the transfected cells into inbred BALB/c mice." (PMID 20950440, 2010).